RNU6-1207P (RNA, U6 small nuclear 1207, pseudogene)
Gene: Small nuclear RNA gene on chromosome 10 (45,188,790 to 45,188,896, reverse strand). Ensembl gene ENSG00000207071.
Homologues: Orthologues: chimpanzee U6 (98% identical), macaque U6 (93% identical), dog U6 (70% identical), rabbit U6 (69% identical), pig U6 (67% identical), rabbit U6 (64% identical). Paralogues in human: RNU6-811P (96% identical), RNU6-1210P (93% identical), RNU6-1293P (93% identical), RNU6-156P (93% identical), RNU6-458P (92% identical), U6 (92% identical), RNU6-1132P (91% identical), RNU6-452P (91% identical), RNU6-614P (91% identical), RNU6-721P (90% identical), U6 (90% identical), RNU6-666P (88% identical), and 1285 more.